AHR (aryl hydrocarbon receptor)
Diseases named in the same sentence as AHR in open-access papers (continued):
Sharing a sentence is not in itself a finding about the gene and the disease.
infection (continued). "Consequently, it is tempting to hypothesize that, in SARS-CoV-2-mediated infection, the initial involvement of AhR could be mainly evoked by increased levels of its agonist Kyn." (PMID 35203299, 2022). "Collectively, AhR activation participates in many diseases; however, it is unclear whether and how AhR activation regulates the development of infection-induced inflammation in remote organs and the effects of dietary Trp and commensal probiotic supplementation." (PMID 35727038, 2022). "Thus, therapeutic targeting of AHR should consider not only its effects on the immune response but also its important roles in the host–microbiome relationship and the multiple effects of the microbiome in autoimmunity, cancer, and infections." (PMID 33408340, 2021). "Therefore, consistent with reported literature, activation of an AhR-mediated host immune system is an additional mechanism by which I3C may exert its Cr infection/inflammation protective effects." (PMID 32230738, 2020). "Thus, we speculate that the binding of the AhR to the ligand after IV infection induces the oxidation of DNA, protein, and lipid components within cells to produce ROS at a higher level, thus leading to apoptosis and autophagy." (PMID 32689931, 2020). "In particular, microbial ligands working as AhR agonists may play a beneficial activity in the regulation of mucosal homeostasis, for instance by promoting epithelial barrier integrity, thus increasing the resistance to infection, and, in turn, AhR may regulate the composition of the microbiome." (PMID 33322584, 2020). "Because AhR responds differentially to diverse intrinsic and extrinsic ligands and affects multiple types of immune cells, a careful examination of the advantages and disadvantages of these AhR antagonists is required to assess their value in the treatment of IV infection." (PMID 32689931, 2020). "We propose a model in which a threshold of AhR activation exists and may explain how activation or inhibition of AhR-derived signals by infection/inflammation-induced ligands, therapeutic interventions or exposure to pollutants can modulate infections/diseases outcomes or vaccination efficacy." (PMID 30984194, 2019). "AHR deficiency or lack of AHR ligands in mice results in perturbations in the intestinal microbial composition, causing the animal to become more susceptible to infection by Citrobacter rodentium and Listeria monocytogenes." (PMID 31653062, 2019). "This indicates that binding affinity and metabolism may be stronger predictors of immune effects than a compound’s source of origin, and that harnessing AHR will require finding a balance between dampening immune-mediated pathologies and maintaining sufficient host defenses against infection." (PMID 29379138, 2018). "Also, by inhibiting NLRP3 expression in macrophages, AhR reduces the inflammatory response and inhibits apoptosis during infection In dendritic cells, AhR activates SFKs, which phosphorylate IDO, leading to increased enzyme activity and production of tolerogenic kynurenines." (PMID 28325761, 2017). "Preliminary findings demonstrate that pharmacological blockade using the AhR antagonist CH223191 or endogenous AhR suppression via recombinant plasmid transfection, significantly inhibits IBV replication during infection." (PMID 41150072, 2025). "Following infection with feline enteric CoV (FECV), strain “München”, a significant activation of AhR and of its target CYP1A1, was observed." (PMID 40006982, 2025). "Following infection in mammalian cells (MDBK), the pre-treatment with a well-known AhR inhibitor, such as CH223191, downregulates AhR signaling, provoking a substantial reduction in virus yield." (PMID 40142473, 2025). "For viruses utilizing AhR activation to enhance antiviral responses (e.g., influenza A virus, IVA), AhR blockade compromises immune defenses and exacerbates infection progression." (PMID 41150072, 2025).
infection (continued). "The activation of the AhR by 2,3,7,8-tetrachlorodibenzo-p-dioxin (TCDD) results in an increased number of neutrophils in the lung during infection with influenza A virus (IAV)." (PMID 38680494, 2024). "Additionally, we propose that targeting the agonist and antagonist of AhR signaling pathways could serve as a promising therapeutic approach for combating pathogen infections, especially in light of the growing prevalence of drug resistance to multiple antibiotics." (PMID 38680494, 2024). "Instead, four IFN expression inhibitory genes (AHR, DUSP1, HES1, and PRDM1) were significantly up-regulated by WT infection." (PMID 37513744, 2023). "In contrast, WT infection induced significantly higher expressions of genes that negatively regulate type I IFN expression, such as AHR, DUSP1, HES1, and PRDM1, compared to the mutant-infected cells." (PMID 37513744, 2023). "The interrelated roles of AHR and HIF-1α signaling play an important role in the coordination of such processes as infection and inflammatory diseases." (PMID 35327980, 2022). "Compared to the ‘PBS+CyHV-2’-infection group, the viral replication in the ‘FICZ+CyHV-2’ group was slower, suggesting that higher AhR expression inhibited CyHV-2 replication in vivo." (PMID 36817692, 2022). "The pharmacologic modulation of AHR activity regulated the expression levels of cytokines induced by infection, specifically, interleukin 1β (IL-1β), IL-10, and TNF-α, supporting a role for AHR activation in the host response to MHV infection." (PMID 33746961, 2021). "A recent study showed that upon the infection of mouse hepatitis virus strain A59 (MHV-A59), a prototypical coronavirus, in bone marrow-derived macrophages (BMDMs), AhR is activated and contributes to the upregulation of PARP7." (PMID 34367175, 2021). "The analysis of mRNA present in the lungs of L-Kyn treated mice confirmed a large increase in the message for AhR and IDO in the two post-infection periods analyzed." (PMID 33936043, 2021). "Lung leukocytes were obtained 96 h, 2 and 10 weeks after infection, and the number of IDO-1+ and AhR+ cells was determined by flow cytometry." (PMID 32647342, 2020). "For example, the “calcium-induced T Lymphocyte Apoptosis,” “Aryl Hydrocarbon Receptor (AhR) Signaling,” “STAT3 Pathway,” and “PCK theta signaling in T lymphocytes” pathways were repressed to a greater extent during APEC O2-GFP infection." (PMID 31998322, 2019). "AHR knockdown significantly impaired HIV-luc/JRFL infection of Magi/CCR5 cells, HIV-luc/VSV-G infection of HEK293T cells (unpaired t test, P < 0.001), and HIV-luc/NL4-3 infection of primary CD4+ T cells (unpaired t test, P < 0.01)." (PMID 31848275, 2019). "However, significant differences in parasite numbers were only observed after 4 weeks using high doses of TCDD in a low dose infection model and may therefore reflect the prolonged activation of AhR in this model which is in contrast to the transient activation by ITE in our experiments." (PMID 31749794, 2019). "The infection efficacy was confirmed by expression of labeled Flag protein and GFP in the RAW/AhR cells." (PMID 30283437, 2018). "To determine at which step the AhR agonist induced a block in the HIV-1 replication cycle, we executed single cycle infection experiments using a VSV-G pseudotyped HIV-1-GFP reporter virus, that expresses GFP in infected cells." (PMID 30132758, 2018). "We found at early phase of the infection, PFOS inhibited the expansion of the pathogen by promoting IL-22 production from the group 3 innate lymphoid cell (ILC3) in an aryl hydrocarbon receptor dependent manner." (PMID 28701769, 2017). "Furthermore, the infection led to the upregulation of CYP1A1 and CYP1B1 levels, which are downstream target proteins in AhR signaling." (PMID 40142473, 2025).
infection (continued). "In order to get more mechanistic insight into the immune cell affected by TCDD and the comparison to constitutive AHR activation, we decided to carry out single cell RNA sequencing combined with ATAC sequencing of cells isolated from colon and c-MLN on day 5 after infection." (PMID 40502009, 2025). "Pharmacological inhibition of AhR using CH223191 has been shown to significantly reduce viral titers of SARS-CoV-2 and human coronavirus 229E (HCoV-229E) in vitro, coinciding with the activation of the AhR pathway during infection." (PMID 41150072, 2025). "Moreover, in infection, TCDD modulated the protein levels of aryl hydrocarbon receptor (AHR), a signaling responsive to both environmental contaminant and CoVs infections." (PMID 39985684, 2025). "However, here for the first time, following infection in bovine (MDBK) cells, the activation of AhR was observed during BCoV infection." (PMID 40142473, 2025). "During NTHi infection of NHNE, indole, produced by the bacteria via the reaction of the TnaA tryptophanase, could have led to activation of AhR." (PMID 38990812, 2024). "Even though in recent years multiple pieces of evidence have been gathered on the effect of AHR during infections, there is still no clear evidence on its role during arenavirus infections." (PMID 36851583, 2023). "Further, AhR and the HIV-1 Tat protein may bind, attracting favorable transcriptional elements that aid in infection." (PMID 37744363, 2023). "Here, the CCoV-induced activation of AhR was noticeably reduced by VER and PS during infection." (PMID 37627739, 2023). "Mechanically, they confirmed that AHR directly binds to the HIV-1 5′ long terminal repeat (5′-LTR) at the molecular level to activate viral transcription and infection, and AHR activation by Trp metabolites increases its nuclear translocation and association with the HIV 5′-LTR." (PMID 36829212, 2023). "Mice lacking AhR in the intestinal epithelium display impaired gut barrier integrity upon infection by the pathogen Cytrobacter Rodentium, allowing bacteria to disseminate to the liver and spleen and accelerate mortality." (PMID 37174049, 2023). "Other evidence came from studies of the saliva of pSS patients, in which it was proved that it activates target genes for AhR (aryl hydrocarbon receptor) and BZLF1 (trans-activator protein—an EBV protein which takes part in switching of the infection phase from latent to lytic)." (PMID 36148238, 2022). "This remarkable pattern indicates that approximately 2/3 of the AhR-regulated genes are the KLF10 target genes as well, supporting the hypothesis that AhR and KLF10 act as a transcriptional axis in response to the infection." (PMID 35397616, 2022). "Indeed, AhR inhibits the production of type I interferons (IFN-I), specifically, during infection with Zika or dengue viruses." (PMID 36366535, 2022). "Importantly, we observed that 4 h and 24 h after infection, higher levels of IFN-β mRNA and IFN-β protein were detected in AHR−/− cell cultures than in their WT counterparts." (PMID 34668726, 2021). "Interestingly, WT and AHR−/− cells treated with the AHR agonist 2,3,7,8-tetrachlorodibenzo-p-dioxin (TCDD) showed comparable levels of infection, an observation consistent with previous studies." (PMID 34668726, 2021). "The animals were sacrificed 96 hours and 2 weeks after infection, their lungs removed, macerated and the leukocytes analyzed by flow cytometry for the intracellular expression of IDO, AhR, and cytokines (IL-12, TNF-α, IL-1β, IL-6, TGB-β, and IL-10) by CD11c+ myeloid cells." (PMID 33936043, 2021). "Upon infection, toll-like receptors TLR bind LPS, which acts as the trigger for the IDO/Kyn/AhR immunotolerance signaling pathway by activating IDO and inducing the expression of AhR." (PMID 34769144, 2021).
infection (continued). "Thus, defining the AhR as an important mechanism that underlies neutrophil migration to the lung may enable the development of safer approaches to treat chronic inflammatory conditions without the increased threat of infection." (PMID 33659010, 2021). "In addition to the increased pulmonary neutrophilia and iNOS levels resulting from IV infection, mice treated with TCDD, which activates AhR only transiently, exhibit a diminished IV-specific CD8+ T-cell response." (PMID 32689931, 2020). "Thus, the AhR agonist 3-HK used as a therapy in T. cruzi-infected BALB/c mice was able to increase the Treg population and to modify the outcome of the infection." (PMID 30984194, 2019). "FICZ treatment activated AHR-mediated signaling, as shown by the significantly enhanced level of CYP1A1 gene expression, and significantly increased the level of HIV-luc/NL4-3 infection (unpaired t test, P < 0.001)." (PMID 31848275, 2019). "Through the AHR expression MPA, may potentially decrease immune function by decreasing T cell IFN-γ and IL-17A production, thereby influencing certain aspects of infection progression." (PMID 31001262, 2019). "Therefore, we considered that weak AhR ligation with 3-HK plus ITE and AhRd mice are good models to study the development of CD8+ T cell memory subsets in this infection." (PMID 30984194, 2019). "In macrophages treated with particles lacking Vpx (SIV3+ ΔVpx), infection using a HIV-1NLYU2-nluc reporter virus was inhibited by ~9 fold by the AhR agonist." (PMID 30132758, 2018). "Conversely, infection of cells depleted of SAMHD1 by treatment with Vpx containing particles (SIV3+) was both enhanced compared to untreated macrophages and was nearly completely resistant to inhibition by AhR activation." (PMID 30132758, 2018). "By comparing the consequences of AHR activation by different types of compounds on the adaptive immune response to IAV infection, we extend our knowledge of ligand-specific, AHR-mediated effects on host responses to infection." (PMID 29379138, 2018). "Thus, after 96 h, 2, and 10 weeks of infection with yeasts, the lung infiltrating leukocytes from the IDO1−/− and WT mice were obtained, and the presence of intracellular IDO1 and AhR in CD11b+ and CD11c+ cells detected by flow cytometry." (PMID 28791025, 2017). "Given that in the primary infection the increase in ASM mass was TLR4 dependent, we next sought to investigate if TLR4 in later life contributed to the development goblet cell hyperplasia, ASM mass and AHR." (PMID 28099113, 2017). "At early stage of infection, PFOS prevents the expansion of C. rodentium by promoting the IL-22 production from the group 3 innate lymphoid cells (ILC3s) through activating aryl hydrocarbon receptor (Ahr), which is a key transcription factor known to regulate the development and function of ILC3s." (PMID 28701769, 2017). "Indeed, by targeting either a single TLR or the AhR pathway while leaving others intact, it may be possible to bring back the inflammatory response within more physiological values, while retaining sufficient host defense mechanisms to avoid exposing patients to adverse risks of further infections." (PMID 28066767, 2016). "It was found that yogurt-derived indole compounds can activate the aryl hydrocarbon receptor (AhR) signaling pathways, promote ILC’s differentiation and proliferation which in turn produces cytokines essential for gut barrier function and protection against infection." (PMID 40538587, 2025). "For example, following CoVs infection with murine coronavirus (MCoV), CCoV type II, Middle East respiratory syndrome coronavirus (MERS-CoV), human coronavirus (HCoV) 229E, severe acute respiratory syndrome CoV type 1 (SARS-CoV-1), and SARS-CoV-2, AhR activation was found." (PMID 40006982, 2025).
infection (continued). "Although not reported in DNA viruses, this mode of action has been found in RNA viruses, where AhR binds directly to the 5′-LTR of the HIV-1 virus at the molecular level, recruiting positive transcription factors into the viral promoter region to facilitate viral transcription and infection." (PMID 40636257, 2025). "Mice lacking AhR exhibit increased susceptibility to L. monocytogenes, despite macrophages displaying heightened production of pro-inflammatory cytokines like IL-6 and TNF-α following infection." (PMID 39767818, 2024). "Surprisingly, the frequency of AhR-dependent Rorγt+FoxP3− Th17 cells, essential for protection against C. rodentium, was increased in the siLPL and mLN of TDD-fed mice; however, IL-17 production from these cells in the colon, the site of infection, was reduced." (PMID 36840944, 2023). "Importantly, PCPA administration failed to exacerbate infection and immunopathology in condition of AhR blockade, whereas 5-HTP administration failed to improve resistance to infection and pathology in condition of IDO1 blockade." (PMID 37717018, 2023). "To understand mechanistically how endothelial-specific AHR activity mediates protection in the lung, we performed bulk RNA-sequencing on pulmonary endothelial cells (CD31+) isolated from naïve and influenza virus infected WT and ECΔAhr mice (day 6 post infection)." (PMID 37587341, 2023). "The AhR antagonist-affected genes were largely unannotated, and the major antimicrobial genes, such as Def1 and Cec1, were not affected, but the genes with potential immune-suppressive functions, such as IAP4, SRPN6, SRPN10 and SOCS require the presence of AhR for the response to infection." (PMID 35397616, 2022). "However, AhR is a promiscuous receptor that can bind multiple ligands with both positive and negative effects on inflammation, immunity, and infections." (PMID 33322584, 2020). "Thus, we show significant and matching effects on footpad swelling, parasite levels and the Th2 response during the first weeks of infection after a very short and local treatment with non-persistent AhR agonist only at the time of parasite inoculation." (PMID 31749794, 2019). "Through evolution, this integration may have stemmed from different behaviors regulated by these families such as pathogen avoidance for bitter taste receptor, detoxification for the AhR pathway and expression of antimicrobial peptides by TLR required for a well-adapted response to infection." (PMID 28066767, 2016). "To further substantiate the biological relevance of LXA4/SOCS2/AhR pathway in controlling pro-inflammatory response during infection with T. gondii, we perform histopathological analysis of the brain and liver tissues obtained from WT, SOCS2-KO and AhRd mice at 30 days after infection." (PMID 22693634, 2012). "However, whether AhR activation mediates infection-induced inflammation in remote organs is not clear." (PMID 35727038, 2022). "Therefore, we can hypothesize that CoVs-mediated infections are facilitated from an inadequate immune response, due in part to the AhR-negative modulation of both IFN-I and NF-κB." (PMID 35203299, 2022). "During infection, the pretreatment of cells with non-cytotoxic doses of CH223191, a selective inhibitor of the aryl hydrocarbon receptor, resulted in a significant reduction in virus yield and a downregulation in the viral spike protein expression." (PMID 40142473, 2025). "Interestingly, although AHR activation increases morbidity and mortality caused by IAV infection, the kinetics of viral growth and the efficacy of the viral clearance, are not significantly different between control and TCDD-treated mice in primary infections nor even during homotypic reinfections." (PMID 33746961, 2021). "These metabolites can activate AHR, an immunomodulatory transcription factor; in the absence of AHR, mice develop AKI and succumb to infection." (PMID 33021470, 2020).